KDM4B (lysine demethylase 4B)
Diseases named in the same sentence as KDM4B in open-access papers (continued):
Sharing a sentence is not in itself a finding about the gene and the disease.
melanoma (4 papers, 2021 to 2025). A malignant, usually aggressive tumor composed of atypical, neoplastic melanocytes. "We show that the relative baseline levels of Kdm4b and Znf217 (a Kdm1a coactivator), determine differentiation state-specific sensitivity of melanoma cells to their corresponding inhibitors." (PMID 33750776, 2021). "KDM4B was also upregulated in primary and metastatic melanomas." (PMID 40940894, 2025). "Together, these data demonstrate that the sensitivity of BRAF-mutant melanoma cells to SP2509 and JIB-04 can be predicted based on their differentiation state (Ngfr versus Axl) and the relative levels of Znf217 and Kdm4b proteins." (PMID 33750776, 2021). "Besides well-established markers of NCSC-like status, a significant increase in expression of lysine demethylase 4B (Kdm4b) has been recently characterized in the Cancer Cell Line Encyclopedia (CCLE) dataset and other 21 human melanoma lines." (PMID 36551603, 2022). "In addition, levels of Kdm4b (but not other JIB-04 targets) were among the top 0.6% proteins whose expression was significantly greater in melanoma cell lines that expressed higher levels of Ngfr relative to Axl." (PMID 33750776, 2021). "Moreover, by analyzing data from TCGA, Kdm4b expression is significantly negative correlated with the majority of immune cell infiltration and positive correlated with cancer prognosis in melanoma." (PMID 40595456, 2025).
acute myeloid leukemia (3 papers, 2019 to 2025). Acute myeloid leukemia (AML) is a group of neoplasms arising from precursor cells committed to the myeloid cell-line differentiation. "The role of KDM4B activity in hematological cancers has been explored in acute myeloid leukemia (AML) and multiple myeloma (MM)." (PMID 30759871, 2019). "In acute myeloid leukemia (AML), WTAP is similarly up-regulated by HIF-1α and stabilizes lysine demethylase 4B (KDM4B) mRNA via m6A modification, driving cancer cell proliferation and survival." (PMID 40102715, 2025).
colorectal tumor (3 papers, 2016 to 2020). "KDM4B overexpression contributes to the genesis of colorectal tumors via its role in beta-catenin mediated gene transcription." (PMID 31335867, 2019). "We first measured KDM4B mRNA levels in 24 primary colorectal tumor samples and corresponding adjacent normal colorectal tissues by quantitative RT- PCR." (PMID 27506941, 2016). "To compare expression levels of KDM4B and HAX1 in colorectal tissues, we performed quantitative RT- PCR and western blot analysis to examine the expression of HAX1 in the 24 primary colorectal tumor samples and 24 adjacent normal colorectal normal tissues." (PMID 27506941, 2016).
glioblastoma (3 papers, 2021 to 2023). The most malignant astrocytic tumor (WHO grade IV). "We have identified KDM4B as a novel factor involved in ALT in ATRX-mutated glioblastomas, and KDM4B can be inactivated either through H3.3G34R or IDH1R132H." (PMID 33972520, 2021). "In conclusion, we provide evidence that inactivation of KDM4B is a critical factor in activating the ALT pathway in ATRX-mutated glioblastomas." (PMID 33972520, 2021). "In this work, we demonstrate that inactivation of KDM4B, through H3.3G34R or IDH1/2 mutations, acts in tandem with ATRX mutations to promote ALT in glioblastomas." (PMID 33972520, 2021). "Immunoblot analysis revealed that KDM4C and KDM4D protein levels were highly expressed in most of the glioblastoma cell lines, whereas the protein levels of KDM4A and KDM4B were very low or not detected." (PMID 33462212, 2021). "KDM4C and c-Myc expressions were positively correlated, whereas those of KDM4A, KDM4B, and KDM4D did not correlate with c-Myc in glioblastoma." (PMID 33462212, 2021).
myeloma (3 papers, 2019 to 2021). "The mechanism underlying the effects of KDM4B on myeloma remains largely unknown." (PMID 35186950, 2021). "However, studies have shown that triptolide decreases the levels of H3K4me2, H3K9me2, and H3K36me2 and induces apoptosis in myeloma cells by altering the expression of KDM4B." (PMID 35186950, 2021). "In contrast to it role in myeloma progression, KDM4B may play a tumor suppressive role in chronic lymphotic leukemia (CLL)." (PMID 30759871, 2019).
thyroid carcinoma (3 papers, 2021 to 2025). "KDM4B overexpression is a bad prognosis for Adrenocortical Cancer and Thyroid Carcinoma." (PMID 35480330, 2022).
alveolar rhabdomyosarcoma (2 papers, 2021 to 2022). A rapidly growing malignant mesenchymal neoplasm. "Genetic and pharmacologic inhibition of KDM4B (JMJD2B) substantially delayed tumor growth in preclinical subcutaneous xenograft models of PAX3-FOXO1-driven alveolar rhabdomyosarcoma." (PMID 36671446, 2022). "A number of histone demethylases are highly expressed in rhabdomyosarcoma and impact on cell proliferation, including KDM4B." (PMID 33917420, 2021). "Here we show high sensitivity of rhabdomyosarcoma cells to a pan-histone demethylase inhibitor, JIB-04 and identify a key role for the histone demethylase KDM4B in rhabdomyosarcoma cell growth through an RNAi-screening approach." (PMID 33917420, 2021). "We determine that KDM4B regulates the expression of cell cycle genes in rhabdomyosarcoma." (PMID 33917420, 2021). "However, after sustained knockdown of KDM4B, rhabdomyosarcoma cell growth recovered." (PMID 33917420, 2021).
asthma (2 papers, 2021 to 2023). "In asthmatic bronchial fibroblasts, the effect of IL-13 has recently been linked to the pathologic involvement of the histone demethylase JMJD2B/KDM4B, which is a major contributor in the development of steroid-resistant asthma." (PMID 37655660, 2023). "Our analysis identified the involvement of a novel gene, namely JMJD2B/KDM4B, in the pathogenesis of subepithelial fibrosis in asthma that is responsive to IL-13 stimulation." (PMID 33688506, 2021).
glioma (2 papers, 2023 to 2025). A benign or malignant brain and spinal cord tumor that arises from glial cells (astrocytes, oligodendrocytes, ependymal cells). "Next, we analyzed the expression of KDM4B in glioma patients using the R2 database, and further evidence indicated that abnormal expression of KDM4B is associated with a poor prognosis in glioma patients." (PMID 38093312, 2023). "Given that abnormal expression of KDM4B is an indicator of a poor prognosis in glioma patients, we investigated the effect of KDM4B on anchorage-independent cell growth and tumorigenesis." (PMID 38093312, 2023). "Collectively, these findings suggest that abnormal expression of KDM4B is an indicator of a poor prognosis in glioma patients." (PMID 38093312, 2023). "KDM4B inhibition by 2HG impairs HR repair in isocitrate dehydrogenase (IDH) mutant gliomas." (PMID 40073141, 2025). "The CNV level of KDM4B increased with increasing glioma grade and was the highest in GBM." (PMID 38093312, 2023). "In addition, KDM4B expression levels in gliomas and GBM tissues were significantly higher than those in normal tissues in the BrainBase database." (PMID 38093312, 2023).
gynecological cancers (2 papers, 2019 to 2021). "More studies are required to determine if the mechanisms regulated by KDM4B in gynecological cancers overlap with pathways targeted by current and emerging chemotherapies." (PMID 30759871, 2019). "KDM4B is required in ER-mediated gene transcription essential not only in mammary gland, but also in ovarian follicles, suggesting a possible correlation of KDM4B between these gynecological cancers." (PMID 34778065, 2021).
Intellectual disability (2 papers, 2016 to 2022). "Studies have shown that the KDM4B overexpression leads to inflammation and intellectual disability." (PMID 35656316, 2022).
metastatic tumor (2 papers, 2017 to 2022). "Nuclear expression of KDM4B in metastatic tumors positively correlated with KDM4B expression in the corresponding primary tumors (Spearman's r=0.7192, P<0.0001)." (PMID 27869162, 2017). "In this study, we have determined that the hypoxia-inducible histone demethylase KDM4B is expressed in ∼60% of EOC tumors assayed, including primary and matched metastatic tumors." (PMID 27869162, 2017).
renal carcinoma (2 papers, 2020 to 2021). A carcinoma arising from the epithelium of the renal parenchyma or the renal pelvis. "In this study, we sought to further investigate the general and unique roles of KDM4B in ovarian, colon, and renal cancer cells." (PMID 34766154, 2021).
skin cutaneous melanoma (2 papers, 2024 to 2025). "Furthermore, survival analysis specifically highlighted that KDM4B expression consistently showed a negative correlation with overall survival in both colorectal adenocarcinoma (COAD) and skin cutaneous melanoma (SKCM)." (PMID 38390756, 2024).
alopecia areata (1 paper, 2024). Loss of scalp and body hair involving microscopically inflammatory patchy areas. "It shows that alopecia areata increased KDM5A, MLL, SETD7, and G9A expression, as well as reduced LSD1, KDM4A, and KDM4B expression." (PMID 39046182, 2024).
autism (1 paper, 2021). Persistent deficits in social interaction and communication and interaction as well as a markedly restricted repertoire of activity and interest as well as repetitive patterns of behavior. "Interestingly, for each of the genes CIB2, FBRSL1, PACS2, KDM4B, and MYT1L, we found 2 individuals with autism with de novo variants in DAEs interacting with these genes." (PMID 34663447, 2021).
autoimmune disease (1 paper, 2025). A disorder resulting from loss of function or tissue destruction of an organ or multiple organs, arising from humoral or cellular immune responses of the individual to their own tissue constituents. "More importantly, the KDM4B–cGAS regulatory axis revealed in this study has significant clinical translation value in tumor immunity and autoimmune diseases." (PMID 40595456, 2025). "Since KDM4B specifically demethylates cGAS at K350, and Kdm4b knockout inactivates cGAS in autoimmune disease, we investigated the significance of cGAS K350 methylation in self-DNA-induced autoimmunity in vivo." (PMID 40595456, 2025). "This difference suggests that targeting KDM4B’s epigenetic regulation offers better specificity and therapeutic efficacy compared to methionine restriction, which broadly affects methylation metabolism, indicating KDM4B as an ideal therapeutic target for autoimmune diseases." (PMID 40595456, 2025). "Given that cGAS hyperactivation can trigger autoimmune diseases such as AGS, we found that KDM4B deficiency or its inhibitor JIB-04 significantly suppresses cGAS activation and IFN expression, providing a novel therapeutic target and strategy for autoimmune diseases." (PMID 40595456, 2025). "Importantly, we show that targeting cGAS demethylation, either through K350R mutation or KDM4B inhibition with JIB-04, ameliorates autoimmune manifestations in both Trex1−/− mice and AGS patient PBMCs, presenting a promising therapeutic strategy for self-DNA-induced autoimmune disorders." (PMID 40595456, 2025).
childhood tumors (1 paper, 2023). "Studies have shown that inhibition of histone lysine demethylase 4B (KDM4B) can delay the growth of tumor cells and inhibit the core transcription factor PAX3‐FOXO1, suggesting that KDM4B may be a potential therapeutic target for malignant childhood tumors such as PAX‐FOXO1+ RMS." (PMID 38090056, 2023).
diabetes (1 paper, 2016). "Treatment also completely reversed diabetes-induced expression changes of Mamdc4, Kdm4b, Tmem252, Selm, and Hpd while others were returned in the direction of normal levels from their diabetes-induced state by ~50%." (PMID 27855634, 2016). "Expression of other coding genes regulated by diabetes with FC > =(+/-) 1.5 and completely reversed by P78 include Mamdc4, Kdm4b, Tmem252, Selm, and Hpd." (PMID 27855634, 2016). "Ugt1a and Mamdc4, which were downregulated and Cyp4a14 and Kdm4b, which were upregulated in diabetes by 2-4 fold also had near complete restoration of expression levels to control by P78." (PMID 27855634, 2016).
diabetic nephropathy (1 paper, 2016). "Cyp4a14 KO mice have increased hypertension and develop diabetic nephropathy when treated with streptozotocin (STZ) compared to wild-type treated with STZ and Kdm4b, a lysine demethylase, plays a role in regulating chromatin structure." (PMID 27855634, 2016).
diffuse intrinsic pontine glioma (1 paper, 2017). A neuroglial tumor that arises from the middle portion of the brain stem. "Beside KDM1, KDM4A and KDM5A/5B are up-regulated in TMZ-resistant GB cells, KDM4B is up-regulated in response to irradiation and KDM6B was identified as a possible therapeutic target in the childhood Diffuse Intrinsic Pontine Glioma (DIPG)." (PMID 28432280, 2017).
insomnia (1 paper, 2022). A sleep disorder characterized by difficulty in falling asleep and/or remaining asleep. "Index SNP rs2249152 (19p13.3, Pmeta = 9.53 × 10–9, mapped gene: KDM4B) was shared between AD and insomnia." (PMID 35656316, 2022).
Leiomyomatosis Renal Cell Cancer (1 paper, 2021). "In addition, increased FH expression also disrupts HR by the inhibition of two key lysine demethylases (KDM4A and KDM4B) in Leiomyomatosis Renal Cell Cancer (HLRCC)." (PMID 33834022, 2021).
liver cancer (1 paper, 2021). An epithelial or non-epithelial malignant neoplasm that arises from the liver. "KDM4B is significantly upregulated in liver neoplasms than normal tissues, whose expression is positively correlated with tumor grade and Ki67, and KDM4B may be a potential diagnostic marker for liver cancer." (PMID 35186950, 2021). "In general, the combined treatment of radiotherapy and KDM4B inhibitors may be an effective strategy for the treatment of liver cancer." (PMID 35186950, 2021).
low grade glioma (1 paper, 2023). A grade I or grade II glioma arising from the central nervous system. "In the GEPIA database, KDM4B expression levels in both GBM and low-grade gliomas (LGGs) were higher than those in normal tissues." (PMID 38093312, 2023).
lymph node metastasis (1 paper, 2020). "Univariate Cox regression analyses indicated that KDM4B expression, lymph node metastasis (N stage), distant metastasis (M stage) and clinical stage were significantly associate with patient survival." (PMID 31931846, 2020). "Furthermore, a multivariate Cox regression analysis further confirmed KDM4B expression, lymph node metastasis (N stage) and distant metastasis (M stage) as independent predictors of shorter OS." (PMID 31931846, 2020).
pancreatic cancer (1 paper, 2021). "In pancreatic cancer, KDM4B has been shown to regulate ZEB1 expression during TGF-β -induced EMT, and silencing KDM4B can significantly inhibit the migration and invasion of pancreatic cancer cells and EMT." (PMID 35186950, 2021).
pancreatic ductal adenocarcinoma (1 paper, 2021). An infiltrating adenocarcinoma that arises from the epithelial cells of the pancreas. "High KDM4B expression was coupled with a good prognosis of overall survival (OS) for patients with BRCA, LIHC, pancreatic ductal adenocarcinoma, HNSC, and UCEC within the pan‐cancer RNA‐seq project (p < 0.05)." (PMID 34766154, 2021).
periodontal disease (1 paper, 2021). "Nevertheless, recent study suggests that inhibition of KDM4B can reduce osteoclastogenesis and suppress pro-inflammatory cytokine release induced by bacteria in periodontal disease." (PMID 33909202, 2021). "Additionally, KDM4B silencing can inhibit pro-inflammatory cytokine release induced by bacteria in periodontal disease." (PMID 33909202, 2021). "Since periodontal disease is a chronic inflammatory disease leading to the teeth damage, we speculate that KDM4B may have important roles in inflammatory diseases." (PMID 33909202, 2021). "Moreover, KDM4B is relevant with osteogenic differentiation in MSCs as well as osteoclastogenesis in periodontal disease." (PMID 33909202, 2021).
Rubinstein-Taybi syndrome (1 paper, 2016). A rare malformation syndrome characterized by congenital anomalies (microcephaly, specific facial characteristics, broad thumbs and halluces and postnatal growth retardation), short stature, intellectual disability and behavioral characteristics. "These include single-gene exonic deletions in NRXN1, GRM8, CREBBP (Rubinstein-Taybi syndrome, MIM:180849), KDM4B, and DMD." (PMID 27257017, 2016).
squamous cell carcinoma (1 paper, 2018). A carcinoma arising from squamous epithelial cells. "More KDM genes, including KDM4B, KDM2B, and KDM4A for adenocarcinomas and KDM2B, KDM4C, and KDM4B for squamous cell carcinomas, appear to be associated with patients’ survival." (PMID 29619118, 2018).
uterine corpus endometrioid carcinoma (1 paper, 2015). "cBioPortal was used to identify relationships between KDM4B and KDM4A expression and disease-free survival (DFS) of uterine corpus endometrioid carcinoma (UCEC) patients (n = 333) in an independent dataset from TCGA network." (PMID 26397136, 2015).
uveal melanoma (1 paper, 2019). A melanoma derived from melanocytes of the uveal tract. "KDM4B expression and activity has also been explored in the progression of uveal melanoma." (PMID 30759871, 2019).
viral infections (1 paper, 2026). "Furthermore, high glucose level upregulates KDM4B, promoting NLRP3 inflammasome activation and IL-1β secretion, thus aggravating aberrant inflammation during viral infections." (PMID 41703092, 2026).